MIR527 (microRNA 527)
Synonyms: hsa-mir-527; MIRN527
Gene: MicroRNA gene on chromosome 19 (53,754,018 to 53,754,102, forward strand). Ensembl gene ENSG00000207979.
Gene Ontology:
Biological process: miRNA-mediated post-transcriptional gene silencing